HOTAIR (HOX transcript antisense RNA)
Diseases named in the same sentence as HOTAIR in open-access papers (continued):
Sharing a sentence is not in itself a finding about the gene and the disease.
cancer (continued). "The lncRNA HOX transcript antisense RNA (HOTAIR), which can reprogram chromatin to promote cancer metastasis, has been found to be overexpressed in HCC, and patients with HOTAIR overexpression had significantly poorer prognosis and higher recurrence rates than those with low HOTAIR expression." (PMID 27239288, 2016). "However, the functional roles of HOTAIR in modulating the cancer epigenome have not been completely elucidated." (PMID 26580594, 2015). "Interestingly, however, most of these reports indicated the presence of subgroups among cancers harbouring low and high levels of HOTAIR expression, irrespective of overall up-regulation of HOTAIR expression." (PMID 26152361, 2015). "Seventh, we could not investigate the role of HOTAIR in different biological subtypes of a given cancer as this distinction was not available for most studies." (PMID 25157956, 2014). "In addition to the independent role of HOTAIR in OS, two other studies respectively found that HOTAIR was an independent factor for cancer metastasis but not for the recurrence of cancer (pooled HR 3.90, 95%CI: 2.25–6.74; pooled HR 1.28, 95%CI: 0.18–9.29)." (PMID 25157956, 2014). "In another study, HOTAIR expression levels were higher in cancerous tissues than in corresponding noncancerous tissues of stage IV CRC patients and those patients with high HOTAIR expression had a relatively poorer prognosis, linking a lncRNA with cancer invasiveness and patient prognosis." (PMID 23680400, 2013). "Because HOTAIR can epigenetically reprogram global chromatin staging and gene expression via its interaction with PRC2, our initial findings warrant further investigation of HOTAIR-mediated epigenetic regulation of the crosstalk between cancer cells and their microenvironment." (PMID 23668363, 2013). "In summary, HOTAIR upregulation may be a negative prognostic factor for NSCLC patients, indicative of poor survival rates and higher risk for cancer metastasis." (PMID 24103700, 2013). "However, many lncRNAs have been found to be differentially expressed in a variety of cancers and may act as either oncogenes, such as MALAT-1, HOTAIR, and ANRIL, or tumor suppressor genes, such as MEG3, lincRNA-p21, and PTENP1, in cancer development." (PMID 24036441, 2013). "Of note, single molecule RNA FISH against HOTAIR in primary lung and foot fibroblast cells showed both nuclear and cytoplasmic localization, and recent chromatin immunoprecipitation experiments have localized HOTAIR in conjunction with PRC2 complex on chromatin in cancer cells." (PMID 23133536, 2012). "Furthermore, accumulating reports of misregulated lncRNA (HOTAIR, MALAT1, HULC, T-UCRs, etc.)expressions across numerous cancer types suggest that aberrant lncRNA expression may be an important contributor to tumorigenesis." (PMID 22613733, 2012). "However, the role of HOTAIR in vasculogenic mimicry has not been studied in human cancers." (PMID 32466537, 2020). "Therefore, miRNAs overexpressed/enriched in the breast are primary candidates as their targeting could not affect the function of the HOTAIR–miRNA axis in non-cancer tissues." (PMID 29469819, 2017). "Thus, HOTAIR might cooperate with PRC2 to maintain mesenchymal and undifferentiated cancer cells." (PMID 25334066, 2014). "However, a study reported that HOTAIR induces repressive chromatin status by promoting the formation of H3K27, suggesting that HOTAIR may function as a tumor suppressor gene by inhibiting proliferation of cancer stem cells." (PMID 25303230, 2014). "Despite HOTAIR’s extensively described role in carcinogenesis, other lncRNAs transcribed from the HOX clusters should not be overlooked in the cancer context." (PMID 33375038, 2020). "The human cancer stem cell marker EpCAM and pluripotency genes Nanog homebox, Oct4 (also known as POU class 5 homeobox 1) and Sox2 do not match HOTAIR’s role as an oncogenic factor." (PMID 31097003, 2019).
cancer (continued). "Salivary HOTAIR and PVT1 were not significantly elevated in BPT patients and patients with any one of eight leading cancers worldwide." (PMID 27028998, 2016). "Majority of CaCx cases portrayed HOTAIR down-regulation in comparison to HPV negative controls, with corresponding up-regulation of HOTAIR target, HOXD10, and enrichment of cancer related pathways." (PMID 26152361, 2015). "However, till now, methylation-dependent interaction between HOTAIR and LSD1 with downstream effects on cancer progression has not been established." (PMID 32209098, 2020). "The evaluation of HOTAIR expression in TME could provide fundamental information, not only for the prognosis, but also for the prediction of the therapeutic response of cancer patients." (PMID 31072041, 2019). "Pterostilbene did not inhibit HOTAIR, MALAT1 or BISPR in MCF7 cancer cells." (PMID 30619763, 2018). "A recently discovered long non-coding RNA, HOTAIR, acts as a trans-regulator to regulate HOXD but not HOXC gene expression during limb development and participates in reprogramming chromatin states to promote cancer metastasis." (PMID 22708672, 2012). "Interestingly, the correlation between HOTAIR and MSLN is not been previously studied on any cell type, thus studying this correlation in TAMs highlights the importance of investigating this relationship in other cell types either cancer cells or immune cells." (PMID 36387279, 2022). "Even though this relation was not reported in the context of cancer but observed in a study investigating the role of TTP and HOTAIR in trophoblasts, it can be assumed that this also holds true for cancerous cells where HOTAIR is generally upregulated and TTP downregulated." (PMID 32340118, 2020).
tumor (586 papers, 2012 to 2026). "Many studies have shown that overexpression of HOTAIR is a risk factor for poor tumor prognosis during tumor invasion and progression." (PMID 40642606, 2025). "The dysregulation of specific lncRNAs, including LINC01140, MALAT1, HOTAIR, and H19, is closely linked to tumor progression, poor prognosis, and resistance to treatment." (PMID 40723840, 2025). "High expression of HOTAIR is closely associated with tumor invasiveness, metastasis, and poor prognosis." (PMID 40621472, 2025). "A dysregulation of HOTAIR has been associated with tumor progression and metastasis in several cancers." (PMID 40149464, 2025). "Clinically, lncRNAs, such as MALAT1, HOTAIR, and H19, are associated with increased microvessel density, tumor progression, and poor prognosis." (PMID 41020820, 2025). "Upregulated H19 promotes cell proliferation and invasion, while HOTAIR, promotes tumour growth, metastasis and angiogenesis and is associated with poor prognosis in colorectal cancer." (PMID 39912983, 2025). "HOTAIR is involved in epigenetic silencing of tumor suppressors and promotes EMT associated with more invasive and resistant cells." (PMID 41020820, 2025). "A high expression of HOTAIR has been associated with advanced pathological stage, tumor progression and increased metastasis, and is an indicator of a poor prognosis and resistance to chemotherapy." (PMID 40868070, 2025). "In our study, the expression of HOTAIR was significantly increased in diffuse GC (p = 0.02), where it is associated with early tumor invasion, higher TNM and metastasis and in intestinal GC (p < 0.0001)." (PMID 40868070, 2025). "The low expression of HOTAIR is linked to a better prognosis, suggesting its potential role as a tumor suppressor in the early stages of NSCLC." (PMID 40723840, 2025). "The results indicated that the expression level of HOTAIR was closely associated with the depth of tumor infiltration as well as TNM." (PMID 38277554, 2024). "For example, the lncRNA HOTAIR has been implicated in the regulation of tumor growth and metastasis by modulating the expression of tumor suppressor genes, such as PTEN." (PMID 39257589, 2024). "In conclusion, these findings suggest that HOTAIR was persistent and substantially expressed, and that it is strongly linked to tumour growth and poor prognosis in EC." (PMID 38981872, 2024). "HOTAIR appeared to cause sponging of miR-148b-3p, and silencing the former resulted in diminution of cell survival, proliferative, and metastasis of tumor cells in a miR-148b-3p-dependent manner." (PMID 38366205, 2024). "Among these, HOTAIR overexpression is linked to advanced tumour node, metastases, drug response, and a worsened CRC prognosis (Sun, Liang and Qian, 2019)." (PMID 38887279, 2024). "Another study has revealed a significant difference in HOTAIR expression between BC and normal tissue and significant associations between HOTAIR gene expression and the tumor size and margin." (PMID 36997931, 2023). "For example, in the case of BC, there is a positive association between the lncRNA HOTAIR and metastasis; HOTAIR acts as a miR-20a-5p sponge, significantly impacting the migration and invasion of tumor cells by modulating the HOTAIR/miR-20a-5p/HMGA2 pathway." (PMID 37348024, 2023). "Studies have shown that HOTAIR is highly expressed in CC tissues and cells, and is associated with tumor proliferation and metastasis." (PMID 37692844, 2023). "The HOTAIR knockdown in tumor cells, indeed, is associated with more miR-30a and −30b released into the exosomes and determines decreased migration, invasion and proliferation of receiving cells." (PMID 37308974, 2023). "This underlines the possible role of exosomal HOTAIR in stimulating immune cell recruitment and mediating tumor–stroma immune interactions." (PMID 37760852, 2023).
tumor (continued). "In BC, lncRNAs are emerging as master regulators of tumour biology, with oncogenic functions associated with tumorigenesis and tumour progression (HOTAIR, MALAT-1, lincRNAp21, and GAS5)." (PMID 35525949, 2022). "Recently, the application of tumor-related lncRNA HOX Transcript Antisense Intergenic RNA (HOTAIR) deletion mutant variant was defined an innovative RNA-based strategy for tumor therapy reported to reduce cellular motility, invasiveness, growth, and EMT." (PMID 35193567, 2022). "Altogether, these results suggest that HOTAIR transcript regulates the expression of multiple metastasis-associated genes by modifying their chromatin accessibility to promote tumor metastasis." (PMID 36579891, 2022). "HOTAIR expression was associated with depth of tumor invasion and tumor location and with shorter overall survival in patients with diffuse-type GC as confirmed in the TCGA cohort." (PMID 35347094, 2022). "HOTAIR expression was associated with depth of tumor invasion (T) with a positivity of 71.4% in T3-4 and 44.4% in T1-2 tumors (P = 0.034)." (PMID 35347094, 2022). "In conclusion, HOTAIR is closely involved in tumor development and associated with chemotherapy resistance." (PMID 36100611, 2022). "HOTAIR propels carcinogenesis and shows an association with tumor initiation and progression, drug resistance, and poor survival rates of patients." (PMID 35248107, 2022). "A notable finding in our work was an association between HOTAIR expression and the depth of tumor invasion." (PMID 35347094, 2022). "The expression of HOTAIR is closely linked with advanced tumor stage, metastasis, and poor prognosis in a variety of human cancers." (PMID 39086963, 2022). "But, we found significant associations between the expression of HOTAIR with the size (P = 0.017) and stage (P = 0.031) of the tumor." (PMID 35186192, 2022). "A study on glioblastoma found that HOTAIR expression was associated with tumor cell proliferation and migration." (PMID 35963868, 2022). "HOTAIR was associated with clinicopathological features of GC patients, including tumor size and tumor stage, suggesting its potential as a diagnostic biomarker in GC." (PMID 35186192, 2022). "In clinical studies, increased HOTAIR expression was associated with advanced tumor stages, higher grades, and metastasis." (PMID 35347094, 2022). "With regard to the clinicopathological features, we observed a significant association between serum HOTAIR expression level and the tumor size." (PMID 33670447, 2021). "HOTAIR overexpression is believed to be associated with the acquisition of stem cell properties, which resulted in an increased tumor growth and metastatic potential." (PMID 34539782, 2021). "HOTAIR (HOX transcribed antisense RNA) was the first lncRNA found to be associated with tumor metastasis, and its upregulation mediates BC invasion and metastasis." (PMID 34079084, 2021). "HOTAIR is significantly overexpressed in RCC cell lines and clinical tissues compared with normal cell lines and tissues, and HOTAIR has been associated with tumor progression and clinicopathological characteristics of patients." (PMID 34367966, 2021). "First identified in 2007, HOTAIR has been shown to be implicated in oncogenic progression and tumor metastasis." (PMID 33461171, 2021). "Numerous studies have shown that HOTAIR can be directly associated with tumor diseases being involved in tumor initiation, growth, angiogenesis, progression, recurrence and drug resistance mechanisms." (PMID 34576322, 2021). "Research on the expression of HOTAIR in macrophages/myeloid-derived suppressor cells (MDSCs) in the tumor microenvironment revealed that HOTAIR is highly expressed by tumor-associated macrophages." (PMID 35011565, 2021). "Expression levels of lncRNAs MALAT1 and HOTAIR analyzed by chromogenic in situ hybridization (ISH) were associated with tumor stages and development of metastases in GEP-NEN." (PMID 34576322, 2021).
tumor (continued). "Here, we found that high expression of HOTAIR was related to adverse clinical features of PCa and associated with tumour insensitivity to docetaxel." (PMID 33024272, 2021). "High HOTAIR expression was also significantly associated with venous invasion (OR = 2.53, 95% CI: 1.12-5.68, P = 0.02), advanced tumor infiltration (OR = 3.35, 95% CI: 1.34-8.42, P = 0.01) and distant metastasis (OR = 5.52, 95% CI: 1.22-25.01, P = 0.03)." (PMID 32104724, 2020). "Next, to identify the altered expression patterns of the specific HOTAIR genotype, rs7958904G>C, we analyzed the expression of the HOTAIR rs7958904G>C polymorphism compared with normal tissue and tumor tissue." (PMID 32117729, 2020). "For example, the aberrant expression of the lncRNA HOTAIR (HOX antisense intergenic RNA) is associated to tumor proliferation, angiogenesis, progression, drug resistance and worse prognosis." (PMID 32460897, 2020). "Further, high HOTAIR expression was found to be associated with venous invasion, advanced tumor infiltration and distant metastasis." (PMID 32104724, 2020). "In the last ten years, the aberrant HOTAIR expression in the majority of solid cancers has been reported, underlining its main role in modulating tumor initiation, growth, angiogenesis, progression, recurrence, drug resistance, and poor prognosis." (PMID 32397382, 2020). "It has been revealed that the HOTAIR expression was positively associated with tumor differentiation, lymph node involvement, and clinical stage." (PMID 31956395, 2020). "HOTAIR upregulation has been associated with tumor aggressiveness and increased metastatic potential." (PMID 32932969, 2020). "Many studies have illustrated the tumor-promoting role of HOTAIR in BC progression and the association between over-expression of HOTAIR in tissues and shorter survival in BC patients." (PMID 31744046, 2019). "It was shown that HOTAIR expression was positively associated with tumor differentiation, lymph node and distant metastasis, and clinical stage." (PMID 31281803, 2019). "Subjects with the TT or CT genotype have higher HOTAIR RNA levels in non-tumor tissues and also higher risk of PTC developing than those with the CC genotype." (PMID 29416703, 2018). "To further assess the prognostic value of HOTAIR polymorphisms, we also performed stratified analyses by age, tumor size, lymph node involvement and different molecular subtypes." (PMID 29423075, 2018). "Recently, HOTAIR has been determined to be overexpressed in most kinds of human malignancies and closely associated with tumor development." (PMID 30111807, 2018). "It is well established that HOTAIR is overexpressed in a wide variety of solid malignancies, and moreover, that this overexpression is associated with metastasis and tumour recurrence." (PMID 29701689, 2018). "One vital mechanism underlying the involvement of HOTAIR in regulating tumour cell proliferation was to modify expressions of relevant miRNAs by acting as competitively endogenous RNAs." (PMID 30030888, 2018). "Experimental over-expression of HOTAIR causes aberrant silencing of tumour suppressor genes, resulting in oncogenically transformed phenotypes." (PMID 28587163, 2017). "HOTAIR expression is also higher in paraffin-embedded NPC biopsies than in non-tumor tissue samples, and high HOTAIR levels are associated with advanced clinical stages and a poor prognosis." (PMID 27802187, 2017). "HOTAIR is overexpressed in a wide variety of solid malignancies and high expression of HOTAIR is strongly associated with metastasis and tumour recurrence in many of these." (PMID 28430163, 2017). "In the present study, we showed that increased expression of HOTAIR in RCC was associated with tumor-lymph node-metastasis (TNM) stage and inversely correlated with prognosis." (PMID 28938586, 2017). "The association between HOTAIR expression and tumor size was analyzed in 26 studies that included 2338 patients." (PMID 28591050, 2017).